TNF (tumor necrosis factor)
Diseases named in the same sentence as TNF in open-access papers (continued):
Sharing a sentence is not in itself a finding about the gene and the disease.
COVID-19 (continued). "The protective effects of the anti-TNFα treatment on the incidence of COVID-19 symptoms reported in our study (RR = 0.50; CI 95% 0.33, 0.75) fully agree with the comments recently published about the urgent need of clinical trials of anti-TNFα therapy for COVID-19." (PMID 33519443, 2020). "Vitamin D may also attenuate exacerbated inflammatory responses by downregulating pro-inflammatory cytokines, such as tumor necrosis factor (TNF)-α and IL-6, involved in the development of cytokine storm during COVID-19-related ARDS." (PMID 33365326, 2020). "The phenomena suggests that the decrease of T cells seen in COVID-19 patients may be the result of high serum concentration of TNF-α, IL-6, and IL-10 negatively regulating T cell survival or proliferation." (PMID 32425950, 2020). "Also, the level of proinflammatory cytokines, such as interleukin 6 (IL-6), IL-2, IL-10, and tumor necrosis factor alpha (TNF-α), highly increases in the serum of severe COVID-19 cases." (PMID 33262791, 2020). "Cytokine-mediated signaling, the natural killer cell mediated toxicity and T cell activation pathways were enriched terms in common between the two disease stages, while Interleukins- and TNF-signaling pathways were enriched terms specific for COVID-19 patients with severe symptoms." (PMID 33129318, 2020). "Cytokine storm was observed in severe COVID-19 patients with high levels of various serum cytokines, such as IL-2, IL-7, IL-10, TNF-α, granulocyte-colony stimulating factor (G-CSF), interferon gamma-induced protein 10 (IP-10; CXCL10), and monocyte chemotactic protein-1 (MCP-1)." (PMID 33251234, 2020). "•Patients on anti-TNF therapy should stop the immunobiological if they develop COVID-19." (PMID 32520223, 2020). "Similar declines were seen in LPS-stimulated TNF-α production by monocytes from COVID-19 patients." (PMID 32687484, 2020). "The remainder of fecal cytokines analyzed (IL-1β, IL-1ra, IL-6, IL-8, IL-17, TNFα) were not significantly different in COVID-19 patients compared to controls nor associated with severity of disease." (PMID 32909002, 2020). "Even though inflammatory cytokine storms were thought to be a mechanism for COVID-19 progression, there was only an increase in IL-2, IL-4, IL-6, IL-10, TNF-α, and IFN-γ when comparing pneumonia patients with healthy people, but no significant increase in severe patients compared to mild patients." (PMID 32985562, 2020). "The mechanism may be related to the rapid and massive production of various cytokines such as TNF-, IL-6, IL-1, and IL-8 in body fluids when patients were infected with COVID-19." (PMID 33013395, 2020). "Although IL-6 is regarded as a marker of pneumonia in CoV infections, it has now become evident that abrupt release of IL-1β and TNF-α could contribute to the severity of CoViD-19 pathogenesis." (PMID 32574269, 2020). "We characterized the ex vivo ability of different leukocyte subsets of patients admitted to the hospital with COVID-19 to produce GrB, perforin, tumor necrosis factor (TNF-α) and interferon-gamma (IFN-γ) after short-term ex vivo stimulation with phorbol myristate acetate (PMA)/ionomycin." (PMID 32707842, 2020). "Nevertheless, in COVID-19 patients, we observed higher IL-6:IL-10 and TNF-α:IL-10 ratios that could reflect an unbalanced overproduction of IL-10." (PMID 33272291, 2020). "Indeed, SAgs induce an inflammatory cytokine signature similar to that which predicts severity and death in COVID-19, including IL-6, TNFα, IL-8, and IL-1β." (PMID 32989130, 2020). "Although many genes are known to be involved in the cytokine storm of COVID-19, we demonstrate that some of the key pro-inflammatory genes (cytokines, interferons, and tumor necrosis factor) are also noted as part of the inflammatory profile in control (no Tocilizumab) patients (control cells)." (PMID 33469465, 2020).
COVID-19 (continued). "In particular, macrophage-related cytokines like interleukin (IL)-1β, IL-6, and tumor necrosis factor-α (TNF-α) were initially reported to be increased in COVID-19 infected patients compared with control subjects, with higher levels of cytokines in severe compared with non-severe infection." (PMID 33505321, 2020). "In support of this hypothesis, patients with more-severe COVID-19 had higher serum levels of IL-2R, IL-6, IL-10, and tumor necrosis factor alpha (TNF-α) than patients with milder disease." (PMID 32616514, 2020). "We hypothesize that the anti-TNF-alpha medication may have interfered with COVID-19’s aberrant immune response, which led to a less severe disease course than expected." (PMID 32824122, 2020). "A cytokine profile resembling sHLH is associated with COVID-19 disease severity, characterized by increased IL-2, IL-7, granulocyte-colony stimulating factor, INF-γ inducible protein 10, CCL1, macrophage inflammatory protein 1-α, and TNF-α." (PMID 32983172, 2020). "However, further investigations concerning the use and safety of TNFα-blockers in COVID-19 patients are urgently needed." (PMID 32467561, 2020). "The significantly decreased levels of CD4+ T lymphocytes and ratio of CD4+/CD8+ lymphocytes and the significantly increased levels of TNF-α and IL-6 in the peripheral blood can be used as important laboratory indicators to assess the severity of COVID-19 in patients." (PMID 32976531, 2020). "In addition, studies regarding TNF-α therapy in COVID-19 are scarce and need urgent attention of the scientific community, given the importance of this cytokine on inflammatory diseases." (PMID 32849309, 2020). "Elevated levels of proinflammatory cytokines IL-6, IL-8 and TNF-α appear to predict patient survival suggesting that imbalanced immune activity resulting from evolutionary mismatches seems to be the primary driver of COVID-19 morbidity and mortality." (PMID 33235797, 2020). "The infection-related biomarkers including SF markedly elevated in the serum as well as Inflammatory cytokines including IL-6, and TNF-α, indicating that inflammation storm may also occur and aggravate in patients died from COVID-19 during the disease." (PMID 32841294, 2020). "We support the appeal by others for anti-tumor necrosis factor therapies for COVID-19." (PMID 32922301, 2020). "A high dose of vitamin B6 administration may reduce the TNF-α, IL-6, and D-dimer levels and improves endothelial integrity along with preventing coagulopathy in COVID-19 patients." (PMID 33195370, 2020). "Notably, a study of nearly 4,000 patients has found the levels of IL-1, IL-6, and TNF-α to be significantly elevated in the sera of patients suffering from severe COVID-19 as compared to those with mild disease (Wanget al., 2020a)." (PMID 33082935, 2020). "Interestingly, COVID-19 patients who died appeared to have the most profound suppression of TNF-α and IFN-ɣ production, and the immune suppression was sustained through at least the first 3 weeks after ICU admission." (PMID 32687484, 2020). "In COVID-19 the homeostatic equilibrium between TREG cells (IL-10) and Th17 cells (IL-17) is broken: inflammatory cytokine levels (IL-1, TNF) are elevated in the lungs of COVID-19 patients, resulting in an increase in HA-synthase-2 (HAS2) in alveolar epithelial cells CD31+, EpCAM+ and fibroblasts." (PMID 33160363, 2020). "A diet rich in such compounds may help patients with COVID-19 to reduce their inflammation due to the hyper-activation of cytokines such as TNFα, IL-1β, IL-6, and IL-8." (PMID 33322757, 2020). "Indeed, anti-TNFα compounds showed a decreased COVID-19 incidence that was higher in women (RR = 0.33; CI 95% 0.17, 0.64) than in men (RR = 0.76; CI 95% 0.41, 1.43)." (PMID 33519443, 2020). "The overproduction of TNF-α in COVID-19 may preferentially activate the NLRP3 inflammasome relative to other immunological pathways." (PMID 32655582, 2020).
COVID-19 (continued). "Indeed, several key inflammatory cytokines associated with hypertension (TNF-α, MCP-1, and IL-6) overlap those elevated in COVID-19." (PMID 32848776, 2020). "Consequently, clinical trials based on TNF inhibitors have been recently proposed in patients with COVID-19." (PMID 33424586, 2020). "In addition, COVID-19 patients in intensive care units showed elevated serum levels of granulocyte colony-stimulating factor, IP-10, TNF-α, MCP-1, and macrophage inflammatory protein 1A respective to patients from general areas." (PMID 32983172, 2020). "From the literature studying sepsis, non-related to COVID-19, a previous meta-analysis had found an improved survival, in particular 28-day all-cause mortality, with monoclonal anti-TNF antibodies." (PMID 33426360, 2020). "However, we also found that severe COVID-19 is accompanied by the IFN-I response in addition to the TNF/IL-1β response." (PMID 32651212, 2020). "Inflammation is closely related to severity of COVID-19, and IL-6 and TNFα might be promising therapeutic targets." (PMID 33349241, 2020). "Therefore, immunomodulators like TNFα inhibitors in addition to anticoagulants and antiplatelet agents are recommended in the treatment of COVID-19." (PMID 33118741, 2020). "Interleukin 6 (IL-6), interferon gamma-induced protein 10 (IP-10), tumor necrosis factor (TNF) α and interleukin 1β (IL-1β) implicated as inflammatory factors associated with COVID-19 progression were detected in the alveoli with diffuse immune cell infiltration." (PMID 34676085, 2020). "Analysis of COVID-19 patients revealed that IL-2, IL-6, IL-7, IL-10, granulocyte stimulating factor, interferon γ inducible protein 10, monocyte chemoattractant protein 1, macrophage inflammatory protein 1-α, and tumor necrosis factor α were increased." (PMID 32948238, 2020). "In this regards, bioactive phytochemicals, such as polyphenols may become promising tools for the treatment of COVID-19 in reducing the hyperactivation of cytokines such as TNFα, IL-1β, IL-6, and IL-8." (PMID 33322757, 2020). "Importantly, TNF-α in the lungs of COVID-19 patients induces HA-synthase-2 (HAS2) in EpCAM+ lung alveolar epithelium and CD31+ lung alveolar endothelium and fibroblasts." (PMID 32961074, 2020). "Elevated levels of CRP, TNF-, and IL-6 are involved in COVID-19 pathogenesis and may act as potential biomarkers for the management of the severity of the disease." (PMID 33244370, 2020). "In a recent study, local TNF-α and IL-1β levels were assessed in COVID-19 patients." (PMID 33013637, 2020). "Further, interleukin 10 (IL-10), interleukin 6 (IL-6), interleukin 1 (IL-1), interleukin 2R (IL-2R), and tumor necrosis factor alpha (TNF-α) levels might exceed the upper limit in COVID-19 patients." (PMID 32516940, 2020). "Indeed, an urgent demand for clinical trials of anti-TNFα therapy for COVID-19 has been proposed recently." (PMID 33511147, 2020). "Other inflammatory cytokines such as IL-1β, IL-4, IL-2, IL-10, and TNFα have also been found to increase, with IL-6 and TNFα still increased in patients with a neurological symptom profile, and IL-1β was upregulated in patients with persistent COVID-19 symptoms." (PMID 41516418, 2026). "However, another study warns against anti-TNF-α therapy in COVID-19 patients as it could augment the SARS-CoV-2 receptor and increase the risk of infection through Notch-1 signaling." (PMID 39745465, 2025). "Besides the role in supporting viral replication, MAPK3 hyperactivation can trigger inflammation (e.g., IL-6, TNF-α) and lung epithelial damage, central to severe COVID-19, and today, MAPK pathway inhibitors are under investigation to mitigate inflammation and viral replication." (PMID 41227320, 2025).
COVID-19 (continued). "Our results indicate that stimulation with TNF-α or thrombin augments fibrinolytic factors, including PAI-1, tPA, and uPA gene expression/protein secretion in HCAECs, a phenomenon linked to the cytokine storm in various pathological states, including stroke, trauma, and COVID-19 [25,]." (PMID 40709224, 2025). "This leads to the upregulation of pro-inflammatory cytokines such as Interleukin-6 (IL-6), TNF-α, and IL-1β and contributing to the cytokine storm, a hyperinflammatory state characterized by the uncontrolled systemic release of cytokines and pulmonary pathology seen in critical COVID-19 patients." (PMID 41176818, 2025). "Consequently, persistent elevations of IL-6 and TNF-α—often seen in patients with severe COVID-19—may substantially contribute to accelerated cellular aging through both telomere erosion and diminished telomere maintenance." (PMID 41154334, 2025). "hsa-mir-26b-5p and hsa-mir-26a-5p are thought to modulate antiviral immune responses, particularly in TNF-α and IFN signaling pathways, while hsa-mir-98-5p is frequently associated with inflammatory responses and cytokine release syndrome, potentially contributing to the pathophysiology of COVID-19." (PMID 40408617, 2025). "However, elevated plasma levels of TNF-α have been identified in individuals with severe COVID-19 in previous studies, and higher levels of IL-10 have been observed in patients with COVID-19 compared to healthy individuals and also in severe cases of the disease compared to non-severe cases." (PMID 39859379, 2025). "In addition to elevated levels of high-sensitivity C-reactive protein (hs-CRP), COVID-19 patients with myocardial injury also presented with low lymphocyte count, and high levels of IL-6, IL-8, N-terminal pro-B-type natriuretic peptide (NT-proBNP) and TNF-α." (PMID 40438117, 2025). "Therefore, future studies should investigate the spatial and temporal dynamics of TNF-α regulation across different tissue compartments, which may provide valuable insights into its immunomodulatory role in COVID-19." (PMID 40661964, 2025). "Nucleotide variants of single nucleotide polymorphisms (SNPs) (TNF-α, interferon (IFN)-λ, human leukocyte antigens (HLA), and interleukins) are involved in the innate and adaptive immune response, which is strongly associated with a causal link to the pathologic progression of AIH and COVID-19." (PMID 39958350, 2025). "In the context of COVID-19, kefir demonstrated antimicrobial and immunomodulatory activity by downregulating the expression of pro-inflammatory cytokines such as interleukin-6 (IL-6), interleukin-1 (IL-1), tumor necrosis factor-alpha (TNF-α), and interferon-gamma (IFN-γ)." (PMID 40647113, 2025). "Additionally, known stress-induced cytokine surges (e.g., IL-6, TNF-α) or microcirculatory impairment during acute COVID-19 could impact follicular health in a patient-specific manner." (PMID 41298780, 2025). "Additionally, these botanical drugs suppressed the production of proinflammatory cytokines, such as IL-6 and TNF-α, both of which have been implicated in the cytokine storm that is associated with ARDS, which is a major cause of death in patients with COVID-19." (PMID 40385477, 2025). "Furthermore, in COVID-19–related ARDS, the systemic release of proinflammatory cytokines such as interleukin, interleukin-6, and tumor necrosis factor-α, caused both by the virus infection and ventilator-induced lung injury, can activate proapoptotic pathway and fibrosis in the kidneys." (PMID 38899195, 2024). "Similarly, increased levels of interleukin-1 (IL-1), IL-6, IL-7, IL-10, tumor necrosis factor-alpha (TNF-α), and reduced expression of interferons (IFNs) have been associated with negative outcomes in individuals with COVID-19." (PMID 38601541, 2024).
COVID-19 (continued). "The SARS-CoV-2-specific polyfunctional Th1 CD4 T cell response (characterized by the co-expression of IFN-γ, TNF-α and/or IL-2), as seen in seropositive children, may be necessary for effective viral control and has been documented in COVID-19 convalescent adults." (PMID 38235336, 2024). "Although not previously associated with COVID-19, sphinganine-1-phosphate showed anti-inflammatory properties by attenuating neutrophil infiltration in the kidneys and liver and reducing plasma levels of IL-6 and TNF-α." (PMID 39595969, 2024). "A long-lasting cytokine signature with high levels of interleukin (IL)-1, IL-6, and tumour necrosis factor (TNF) may be responsible for many of the clinical signs of Post-acute sequelae of COVID-19 (PASC) and may originate in the macrophage compartment, according to one study." (PMID 38544825, 2024). "While the absence of an association between TNF -308G/A and COVID-19 outcomes could be attributed to a lack of statistical power due to small sample sizes, it is less likely given the minimal differences in allele and genotype frequencies (less than 2%)." (PMID 38675991, 2024). "They found that 6-MSITC reduces the production of proinflammatory cytokines, such as IL-6 and TNF-α, and lowers the adhesion of immune cells to endothelial cells, which are crucial factors in the development and progression of inflammation and cytokine storms in patients with COVID-19." (PMID 39459194, 2024). "Post- receptor signals linking TNFα to cathepsin B hyper-catabolism in various cell types are unknown; however, this protease is a major player in the execution of myocardial tissue injury from pro-inflammatory cytokines that are operative in COVID-19." (PMID 38578560, 2024). "Likewise, IL-6 and TNF-α were considerably upregulated in COVID-19 patients." (PMID 38849961, 2024). "Therefore, the higher severity of agitated depression in females could be driven by gender-specific high levels of TNF-α during COVID-19, which could remain high after SARS-CoV2 infection." (PMID 39199439, 2024). "Th1 cells observed in individuals with COVID-19 demonstrated a distinctive expression of CXCR3 and CCR6, in addition to transcripts encoding cytokines and chemokines with anti-viral properties, such as CD154, IFN-γ, IL-2 (interleukin-2), and TNF (tumor necrosis factor)." (PMID 38675727, 2024). "Notably, pathogen-related pathways such as Coronavirus disease - COVID-19, Legionellosis, and Salmonella infection, along with immune-related pathways like Antigen processing and presentation and TNF signaling pathway, were all found to be downregulated in M-AD compared to F-AD." (PMID 38689734, 2024). "Thus, urinary proinflammatory cytokines such as TNFα, IL-1α, IL-1β, IL-16, and IL-17A and total uEVs in COVID-19 patients may identify patients that are prone to renal dysfunction." (PMID 38398672, 2024). "TNF-α-GA and AA genotypes and A allele, IL-8 TA and AA genotypes and A allele and CXCR-2 CC and CT genotypes have significant associations with mortality risk in COVID-19 patients, while GA and GG genotypes of the IL-10 are shown to confer significant protection against mortality from COVID-19." (PMID 38544825, 2024). "The importance of inflammatory cytokines such as TNF-α and IL-6 is further demonstrated by the fact that blockade of individual cytokines resulted in a partial rescue of cardiomyocyte viability, confirming serological cytokine-driven cardiotoxicity in COVID-19." (PMID 38041432, 2024). "However, several other studies suggested that immunosuppressants may be beneficial to patients infected with COVID-19 by mitigating cytokine storms, such as anti-interleukin (IL)-6 antibodies and anti-tumor necrosis factor (TNF) therapy." (PMID 39538233, 2024).